PDIA3 (protein disulfide isomerase family A member 3)
Diseases named in the same sentence as PDIA3 in open-access papers (continued):
Sharing a sentence is not in itself a finding about the gene and the disease.
cancer (continued). "Our results confirmed that PDIA3 is a robust prognostic biomarker for pan-cancer and predicts the immunotherapy response effectively, and it provided a main thread for further investigation on the role of PDIA3 in cancer immunity." (PMID 35401558, 2022). "PDIA3 expression has been proved to be a prognostic biomarker of many cancers, and it is considered as a possible new pharmacological target, which plays a vital role in the occurrence and development of many cancers." (PMID 36046686, 2022). "Therefore, we think that both of PDIA5 and PDIA3 promote the progression of human cancers through affecting the infiltrated immune cells in tumor microenvironment, and the underlying mechanism remains further exploration." (PMID 36003400, 2022). "Interestingly, literature search for the last 10 years revealed that PDIA3 (also ERp57 or GRP58) along with AGR2 had attracted the most attention in relation to cancer research." (PMID 34929376, 2022). "Therefore, PDIA3 is one of the reasonable candidate biomarkers for studying cancer prognosis and can be used as a target for cancer treatment." (PMID 36406049, 2022). "In previous studies, EMT has been significantly confirmed to be related to the occurrence, metastasis, and drug resistance of cancers, suggesting that PDIA3 might play an indispensable part in the oncogenesis and development of cancers by enrolling in EMT." (PMID 35401558, 2022). "Our result is in line with previous observations suggesting PDIA3 as a key protein that might contribute to cancer development." (PMID 33761087, 2021). "Interestingly, this study indicates for a correlation between the ratio of PDIA3N/PDIA3 and cancer stage." (PMID 33761087, 2021). "A potential role on the mechanisms regulating GAM activity might be played by the endoplasmic reticulum protein ERp57/PDIA3 (protein disulfide-isomerase A3), the modulation of which has been reported in a variety of cancers." (PMID 33153019, 2020). "In addition, in several cancer cell lines, the knockdown of PDIA3 affected different pathways involved in its physiological functions." (PMID 33153019, 2020). "Alterations in PDIA3 abundance have been correlated with poor prognosis in several cancers." (PMID 33095243, 2020). "The prognostic value of the PDIA3 in pan-cancer was also assessed." (PMID 32687065, 2020). "In addition, PDIA3 expression in cancer cells is critical for tumor cell resistance to thermotherapy in A549 and UO31 cancer cell lines." (PMID 23782473, 2013). "Additionally, intense expression of PGAM1, HSPD1, and PDIA3 was observed in the cytoplasm of cancer cells in both hilar and intrahepatic CC." (PMID 23118872, 2012). "In particular, high PDIA3 protein levels in Gleason pattern 3 cancers may indicate the presence of more aggressive tumor foci in the same tissue and could be of diagnostic value, possibly as part of a larger molecular signature." (PMID 20035634, 2009). "Furthermore, PDIA3 expression showed significant correlations with cancer stage and tumor grade." (PMID 37909009, 2023). "However, further studies are needed to investigate whether PDIA3 plays a role in cancers by activating the PI3K/AKT signaling pathway." (PMID 38213579, 2023). "In addition to the AKT pathway, other signaling pathways have also been reported to be involved in PDIA3-mediated biological functions in cancers, such as STAT3 signaling, EGFR signaling, 1alpha, 25-dihydroxy vitamin D3 [1,25(OH)2D3]-mediated pathway and mTOR signaling." (PMID 38213579, 2023). "This indicated that PDIA3 might play different roles in distinct cancer types." (PMID 35401558, 2022). "Moreover, our results could provide some clues for further investigation to recover the potential role of PDIA3 in cancer immunity and immunotherapy." (PMID 35401558, 2022). "Thus, choosing the suitable inhibitor of PDIA3 is needed to target PDIA3 for cancer therapy." (PMID 35401558, 2022).
cancer (continued). "Studies have shown that PDIA3 plays a key role in maintaining the antitumor immune response, which may become a potential cancer treatment target, used for the treatment of tumors that previous treatments have failed to induce strong T cell-mediated immune response." (PMID 36046686, 2022). "The GSEA result suggests that PDIA3 is closely associated with immune-activated processes, such as TNFA-signaling-via-NFKB, IFN-α response, IFN-γ response, inflammatory-response, and allograft-rejection pathways, but completely opposite results were observed in distinct cancer types." (PMID 35401558, 2022). "PDIA3 may be a potential indicator of the efficacy of cancer immunotherapy." (PMID 36046686, 2022). "In addition, PDIA3 is significantly correlated with immune-activated hallmarks, cancer immune cell infiltrations, and immunoregulators, and the most interesting finding is that PDIA3 could significantly predict anti-PDL1 therapy response." (PMID 35401558, 2022). "Therefore, we believe that PDIA3 could be a robust immunotherapy biomarker for cancers, and it possesses the strong potential to be applied in clinical cancer treatment." (PMID 35401558, 2022). "Thus, a shift in ratio between PDIA3N and PDIA3 may contribute to cancer progression by decreased redox activity and altered hormone function." (PMID 33761087, 2021). "However, PDIA3 has been found in different subcellular compartments where it has been proposed and sometimes proved to be involved in a remarkable variety of cellular processes and in pathological conditions including cancer and neurodegenerative diseases." (PMID 28044092, 2016). "In contrast, a few individual genes, such as BAX, CLAR, HMGB1, HSP90A11, IFNA1, and PDIA3, showed weak correlations with the ICD scores in most cancer types." (PMID 38627900, 2024). "Previous studies find the correlation between PDIA3 and NRP1, CD276 was also very significant in pan-cancer." (PMID 37251370, 2023). "Many of these hits are serum proteins described to have aberrant N-glycosylation during cancer progression, such as AFP and the protein disulfide isomerase PDIA3." (PMID 36961502, 2023). "To obtain a broader view of the functions of PDIA3 in cancer cells and to identify more potential mechanisms for the role of PDIA3 in human cancers, we performed GSEA for the differential genes related to PDIA3." (PMID 38213579, 2023). "The protein disulfide isomerase A3 (PDIA3) is directly or indirectly involved in various physiopathological processes and participates in cancer initiation, progression and chemosensitivity." (PMID 37686085, 2023). "Protein disulfide isomerase (PDI) A3 (PDIA3) is a crucial member of the PDI family and has recently attracted attention for its effect on human cancer owing to its broad significance in disease development." (PMID 36894874, 2023). "The expression of PDIA3, PDIA4, PDIA6, ERP29, and TXNDC5 have also upregulated in most cancer types." (PMID 35965326, 2022). "In both normal and cancer prostate tissues, VDR is found to be lower both at level of transcription and translation compared to PDIA3." (PMID 33761087, 2021). "Microarray data analysis has demonstrated the upregulation of several typical PDI members including PDIA1, PDIA3, PDIA4 and PDIA6 in multiple cancers such as breast, colorectal, liver, brain and prostate." (PMID 33742523, 2021). "PDIA3 (also known as ERp57), an important member of the protein disulfide isomerase (PDI) family, has drawn the attention of researchers to explore its role in human cancers due to its widespread implication in disease development." (PMID 32687065, 2020). "In this regard, it should be noted that PDIA3 modulates STAT3 signaling and that PDIA3 up- or downregulation has been related to cancer progression and inhibition of proliferation, respectively, through STAT3." (PMID 33153019, 2020).
cancer (continued). "The expressions of MYC, PDIA3, and ITGA5B1 have been demonstrated to play critical roles in various malignant tumors and are independent prognostic factors in certain cancers." (PMID 31886273, 2019). "Notably, CASP1 was consistently elevated in normal tissues across most cancers, whereas FOXP3 and PDIA3 were frequently enriched in tumors." (PMID 41150760, 2025). "In recent years, PDIA3 has been shown to interact with and regulate the activity of the AKT signaling pathway, a key regulator of cell growth, survival, and metabolism in several types of cancer." (PMID 38213579, 2023). "PDIA3 has been shown to interact with and regulate the activity of AKT and modulate the downstream signaling of the PI3K/AKT pathway, which is a key regulator of cell growth, survival, and metabolism in other types of cancer." (PMID 38213579, 2023). "Altogether, our results show that targeting PDIA1 and PDIA3 as well as PDIA17 might afford effective anti-cancer effects, particularly in highly malignant cancer cell types by targeting cancer cell adhesion." (PMID 35725466, 2022). "Although more and more studies have shown that PDIA3 plays an important role in the occurrence and development of many tumors, there is no systematic pan-cancer study on PDIA3." (PMID 36046686, 2022). "HMOX1, ARRB1, and PDIA3 were significantly differentially expressed in LUAD-normal and LUAD-cancer." (PMID 35957802, 2022). "Likewise, other PDI members namely PDIA3, PDIA4, and PDIA6 are also highly expressed in numerous cancer types including breast, thyroid, rectal, gastric and liver cancers." (PMID 35965326, 2022). "PDIA3 is well-known as an essential component for MHC Class I peptide loading complex which presents antigen to CD8 + cytotoxic T cells to enable tumor antigen recognition and anti-tumor immune responses, hence it is vital for cancer immunotherapy." (PMID 35965326, 2022). "There is a significant negative correlation between PDIA3 gene expression and tumor mutation load in KIRP, LAML, PRAD, and THCA in the other 4 cancers." (PMID 36046686, 2022). "There is a significant negative correlation between PDIA3 gene expression and microsatellite instability in the other three cancers BRCA, LGG, and PRAD." (PMID 36046686, 2022). "This indicated that tissue type might not be an essential determinant contributing to ICD state of cancer patients; instead, a few high-expressed genes including CALR, HSP90AA1 and PDIA3 could regulate the process of ICD at a pan-cancer level." (PMID 36497433, 2022). "The major contribution of PDIA1 and PDIA3 to the total PDI profile of various cancer cells, their secretion and important role outside the cell agrees with growing evidence for the involvement of PDIA1 and PDIA3 in cancer progression." (PMID 35725466, 2022). "PDI family proteins, such as AGR2, PDI, PDIA3, PDIA4, and PDIA6 are reportedly upregulated in cancers, which are correlated with cancer progression and metastatic disease in pancreatic, kidney renal clear cell carcinoma (KIRC), ovarian cancers, glioblastoma and lung adenocarcinoma." (PMID 36202782, 2022). "Besides, there was a robust positive relationship between PDIA3 and CD276 and Neuropilin-1(NRP1) in most of the TCGA cancers." (PMID 35401558, 2022). "Among the 24 adjacent cancer tissues, there were 8 (33.3%) PDIA3 protein positive expression cases and 16 (66.7%) negative expression cases." (PMID 36406049, 2022). "The best described PDI isoforms in cancer cells are PDIA1 (P4HB) and PDIA3 (ERP57)." (PMID 35725466, 2022). "Interestingly, PDIA17 was expressed in some cancer cell lines (e.g., MCF-7, PC-3, HT-29, T47D, A549, NCIH358) with comparable expression levels to that of PDIA1 and PDIA3." (PMID 35725466, 2022). "In conclusion, circRFX3 could act as a cancer-promoting circRNA to boost the development of GBM and regulate the miR-587/PDIA3/β-catenin axis." (PMID 34950658, 2021).
cancer (continued). "Comparison of these selective PDIA1 inhibitors with E64FC26; a potent pan‐style inhibitor which inhibits; PDIA1, PDIA3, PDIA4, PDIA6 and TXNDC5, would give an indication as to whether inhibition of PDIA1 alone is sufficient for suppressing cancer cell growth." (PMID 33742523, 2021). "However, most studies are limited to the role of PDIA3 in specific tumors, and there is no pan-cancer study of PDIA3 in various tumors." (PMID 36046686, 2022). "PDIA1 and PDIA3 represent major isoforms of multiple cancer cells, and their non-selective inhibition displays significant anti-proliferative effects irrespective of whether or not PDIA17 is present." (PMID 35725466, 2022). "Recent studies have shown that several PDIs, such as PDIA1, PDIA3 and PDIA6, are upregulated in different cancer types, including kidney, lung, brain, ovarian, melanoma, prostate and male germ-cell tumours, and over-expression of PDIs may serve as a diagnostic marker for cancer." (PMID 33023153, 2020). "Therefore, we infer that CALR and PDIA3 exert a positive or negative effect on prognosis of patients with cancer by regulating the cancer cells themselves or the immune responses in the tumor microenvironment." (PMID 29228584, 2017). "However, the remaining eight cancer-specific DESPGs of GLB1, HSPA5, PDIA3, GNRH1, IFNGR2 ADAM9, TPST2, and TAC4) were not reported in any researches, which could be potential novel prognostic biomarkers in corresponding tumors." (PMID 31824949, 2019).
tumor (100 papers, 2008 to 2026). "Meanwhile, PDIA3 is capable of facilitating the polarization of M2 tumor-associated macrophages through activating the STAT3/PD-1 signaling, thereby greatly enhancing the progression of colorectal cancer." (PMID 41185082, 2025). "Substantial evidence has emerged linking PDIA3 to the promotion of M2-polarization in tumor-associated macrophages and the enhancement of tissue protease secretion, mediated by the STAT3/PD-1 signaling cascade." (PMID 38761176, 2024). "Intriguingly, PDIA3 was found to promote an M2 macrophage phenotype in tumor-associated macrophages and increase tissue protease secretion through the STAT3/PD-1 axis." (PMID 38761176, 2024). "Is the putative role of PDIA3 in the M2 polarization of tumor-associated macrophages overly magnified?" (PMID 38761176, 2024). "PDIA3 has also been identified on the surface of tumor-associated macrophages in triple-negative breast cancer specimens and has been suggested as a possible new prognostic marker." (PMID 36374169, 2023). "The increased expression of PDIA3 in tumor tissues and its association with poor prognosis indicates an oncogenic role of PDIA3 in OSCC." (PMID 38213579, 2023). "Several reports suggested that PDIA3/ERp57 is associated with tumor progression and the modulation of STAT3 activity." (PMID 28489571, 2017). "In conclusion, positive expression of CCT2 and PDIA3 are associated with large tumor size, high TMN stage, lymph node metastasis, adjacent tissue invasion, and poor prognosis of SC/ASC and AC." (PMID 23782473, 2013). "Recent scientific discoveries have shed light on PDIA3's influential role in modulating the behavior of tumor-associated macrophages, in particular, its regulatory capacity over the STAT3/PD-1 (signal transducer and activator of transcription 3/programmed cell death protein 1) signaling axis." (PMID 38761176, 2024). "PDIA3 is overexpressed in several tumors, suggesting that tumor cells, and the associated oncogenic pathways, may require higher levels of PDIA3 to support the overexpression or activation of PDIA3-dependent processes compared to normal cells." (PMID 37686085, 2023). "Moreover, GSVA analysis implied that PDIA3 suppressed T cell associated anti-tumour immune response." (PMID 32687065, 2020). "The results of our IHC analysis point to a potential use of PDIA3 as a diagnostic marker: PDIA3 expression of Gleason pattern 3 tumors is higher in the presence of a Gleason pattern 5 tumor than in presence of another Gleason pattern 3 tumor." (PMID 20035634, 2009). "Our analysis revealed distinct expression patterns of CASP1, FOXP3, and PDIA3 between normal and tumor tissues, highlighting their potential roles in shaping the tumor immune microenvironment." (PMID 41150760, 2025). "The genesis of a subdermal neoplasm-bearing murine model in Balb/c mice permitted us to ascertain that the cohort subjected to PDIA3 suppression manifested a pronouncedly antagonistic effect on the tumor compared to the control ensemble." (PMID 38761176, 2024). "Under the condition of co-culture of tumor-associated macrophages and SW480 cells, PDIA3 can promote the expression of PD-1 by enhancing the phosphorylation of STAT3, and PD-1 is then secreted extracellularly." (PMID 38761176, 2024). "A comparative analysis of neoplastic data between cohorts revealed a significant augmentation in tumor volume within the PDIA3 overexpression group, contrasted with a considerable reduction in the sh-PDIA3 cohort as compared to the normoexpressed controls." (PMID 38761176, 2024). "By implementing a subcutaneous xenograft model in BALB/c mice, we discerned that the sh-PDIA3 contingent demonstrated a notable tumor-suppressive effect when contrasted with the control cohort." (PMID 38761176, 2024). "In recent years, several studies have indicated that PDIA3 plays an important role in tumorigenesis, cell proliferation, apoptosis, tumor metastasis, angiogenesis, and chemoresistance." (PMID 38213579, 2023).